INS (insulin)
Diseases named in the same sentence as INS in open-access papers (continued):
Sharing a sentence is not in itself a finding about the gene and the disease.
type 2 diabetes (continued). "In Type II diabetes, patients often retain some insulin production, and the incidence of ketoacidosis is significantly lower than in Type I, where ketoacidosis can occur under stress from illness, such as infection." (PMID 41383402, 2025). "Both type-1 and people with type-2 diabetes use insulin, and people with type-2 diabetes require large doses of insulin at a later stage." (PMID 39190215, 2024). "Due to its high concentration of glycine, collagen has been shown to stimulate insulin secretion and stabilize blood sugar levels in individuals with type 2 diabetes." (PMID 39394552, 2024). "Our study is the first randomized trial to assess the durability of simplification of complex insulin regimens in patients with type 2 diabetes in their current clinical practice." (PMID 37787888, 2024). "GSEA suggested that ENPP3 was enriched in Toll like receptor (TLR) pathway, NUDT12 was enriched in maturity onset diabetes of the young and insulin pathway." (PMID 38464965, 2024). "In patients with diabetes type 2 or impaired glucose tolerance, a recent systematic analysis revealed weak correlations between vitamin D treatment, improved resistance to insulin, and decreased fasting glucose." (PMID 39822434, 2024). "Mice fed with HFD developed type 2 diabetes characterized by increased body weight, fasting blood glucose, fasting serum insulin, total cholesterol and triglyceride in comparison with mice fed with chow diet." (PMID 38664801, 2024). "This FMD regimen can rejuvenate insulin secretion and balance glucose levels in both type 1 and type 2 diabetes mouse models." (PMID 38321992, 2024). "Many clinical studies suggest a positive effect of probiotic therapy in slowing the progress of resistance insulin and, thus, type II diabetes." (PMID 39796443, 2024). "With the anticipated rise in prevalence of type 2 diabetes and earlier age of onset, it is likely that closed-loop systems will have an important role in management of those requiring insulin." (PMID 39390689, 2024). "Insulin increased glycogen synthesis by 1.7-fold (p=0.0031) in myotubes from donors with type 2 diabetes." (PMID 38814443, 2024). "While, initially, lifestyle modifications and oral medications are commonly employed, the progressive nature of type 2 diabetes often necessitates the inclusion of insulin therapy." (PMID 39065795, 2024). "Excessive weight and high insulin doses are independent factors for type II diabetes development following SKPT." (PMID 39606037, 2024). "MicroRNAs, short noncoding RNA molecules, play a pivotal role in regulating β-cell function, insulin production, and resistance, and show promise as biomarkers for predicting type 2 diabetes onset." (PMID 38805166, 2024). "Abdominal pain; carpal tunnel syndrome; flatulence; facial edema; headache; nausea; insulin resistance and possible type 2 diabetes; cardiac instability; hypertension; sleep apnea; abnormal bone growth; muscle weakness; fluid retention." (PMID 39584970, 2024). "Overall, for type 1 diabetes (T1D) and type 2 diabetes (T2D), most physicians indicated < 30% of PwD missed or skipped a bolus insulin dose in the last 30 days (T1D: 83.0%; T2D: 74.1%)." (PMID 38649812, 2024). "This treatment involved the administration of large doses of insulin to induce a hypoglycemic coma in patients, who were then brought out of the coma by glucose injections." (PMID 39734678, 2024). "This suggests heterogeneity of insulin responses in different target tissues among people with type 2 diabetes and is in line with the increasing evidence of heterogeneity of type 2 diabetes." (PMID 38814443, 2024). "Studies suggest that maternal hyperglycemia during pregnancy can induce epigenetic changes in key metabolic genes, such as those involved in insulin signaling, playing a role in the development of type 2 diabetes in offspring." (PMID 39770898, 2024).
type 2 diabetes (continued). "Fundamentally, inducing type 2 diabetes is expected to detrimentally alter both insulin signaling pathways and ROS levels in the hippocampus, contributing to a depressive-like phenotype in mice models." (PMID 39000608, 2024). "Type 2 diabetes is one of the more concerning factors of MetS similar to that of hypertension as once the process of glucose and insulin dysregulation begins the ability to appropriately correct toward baseline levels of glycemic control diminishes rapidly." (PMID 38337589, 2024). "Men with type 2 diabetes had higher BMI, fasting plasma glucose, serum insulin and C-peptide concentrations, HbA1c and HOMA-IR than men with NGT." (PMID 38814443, 2024). "The maximum dose requirement of insulin was 1.68 units/kg/day comparable to doses in women with type 2 diabetes in the third trimester of pregnancy (up to 1.6 units/kg/day)." (PMID 38461278, 2024). "Type 2 Diabetes Mellitus (T2DM) is a chronic metabolic disorder characterized by persistently high blood glucose levels due to the body’s inability to effectively use insulin." (PMID 39550565, 2024). "The largest RCT to date was performed in 110 participants with type 2 diabetes receiving insulin therapy." (PMID 38953925, 2024). "More specifically, it is the accumulation of lipid metabolites, such as diacylglycerols and ceramides, which directly impact insulin signalling leading to impaired insulin-stimulated glucose uptake in obese individuals and type 2 diabetes patients." (PMID 38566151, 2024). "We observed that, in normoglycemic South Asian women, the relationship curve between plasma NEFA and insulin levels was more similar to that seen in women with prediabetes/type 2 diabetes." (PMID 38786765, 2024). "The aim of this work was to examine the impact of hypoglycaemia on daily functioning among adults with type 1 diabetes or insulin-treated type 2 diabetes, using the novel Hypo-METRICS app." (PMID 39080044, 2024). "In contrast, Type 2 diabetes is characterized by insulin resistance and inadequate insulin secretion." (PMID 39707176, 2024). "Type 2 diabetes is a condition in which the body becomes resistant to the effects of insulin, leading to reduced insulin production in the pancreas." (PMID 39071038, 2024). "For example, individuals with type 2 diabetes (T2D) on metformin only treatment will have a very different GV compared to those on multiple daily injections (MDI) of insulin." (PMID 39632776, 2024). "Meanwhile, the development of type 2 diabetes is driven by two key factors: reduced insulin sensitivity and failure of pancreatic beta cell function." (PMID 39596859, 2024). "Intriguingly, the evaluation of mitochondrial density in patients with type 2 diabetes showed a lower number of mitochondria compared to those of age-matched insulin-sensitive individuals." (PMID 39378614, 2024). "Despite the availability of new classes of glucose-lowering drugs that improve glycaemic levels and minimise long-term complications, at least 20–25% of people with type 2 diabetes require insulin therapy." (PMID 38679644, 2024). "The earliest hallmark of type 2 diabetes (T2D) is the loss of first-phase insulin secretion." (PMID 38677509, 2024). "Adults on insulin with type 2 diabetes find rtCGM systems widely acceptable, and easier to engage with than traditional self-monitoring of capillary blood glucose." (PMID 38932793, 2024). "HbA1c reduction with icodec in those with type 2 diabetes was similar to that achieved with once-daily basal insulin analogues, but with a small benefit when icodec was compared with daily analogues without aspart." (PMID 38679644, 2024). "Patients with type 2 diabetes received an intrapancreatic autologous bone marrow stem cell infusion; after 1 year, these patients showed improved metabolic control and reduced insulin requirements." (PMID 38533089, 2024).
type 2 diabetes (continued). "We also performed multivariable MR with adjustment for genetically proxied smoking, body mass index (BMI), waist-to-hip ratio, type 2 diabetes, and fasting insulin for both exposures." (PMID 38583262, 2024). "Our aim was to systematically review and meta-analyze the efficacy and safety of Icodec compared to once-daily insulin analogs in type 1 (T1D) and type 2 diabetes (T2D)." (PMID 39200316, 2024). "As a common feature in metabolic syndrome and type 2 diabetes, IR refers to the diminished sensitivity or impaired response of the target organs or tissues to insulin." (PMID 39416649, 2024). "Genetic sharing was also found in peripheral insulin signaling traits: type 2 diabetes with “aggressive taboo thoughts”, and fasting insulin and 2 h glucose levels with OCD." (PMID 39796465, 2024). "It is important to note that women’s experiences with complex insulin regimes and intense glucose monitoring prior to pregnancy are likely to be very different for individuals with type 2 diabetes compared with those with type 1 diabetes." (PMID 38967667, 2024). "Before every intervention, all patients suffered from insulin-treated type 2 diabetes with poor glycemic control (mean HbA1c ± SD: 8.6 ± 1.7%)." (PMID 38589596, 2024). "In a recent study of a type 2 diabetes rat model, lower HS intensity was reported in male animals, potentially contributing to glucose intolerance and decreased islet insulin secretion in the disease." (PMID 38612775, 2024). "The pathophysiology of type 2 diabetes results in ineffective insulin, an inability to metabolize glucose, and chronic excess blood glucose." (PMID 38769421, 2024). "Other treatments, such as Pioglitazone and Sitagliptin, also used in type 2 diabetes, have different mechanisms of action but ultimately increase insulin sensitization in PCOS." (PMID 39479136, 2024). "Restoring hepatic and peripheral insulin sensitivity is critical to prevent or reverse metabolic syndrome and type 2 diabetes." (PMID 38280549, 2024). "The interplay between gut microbiota and the development of obesity, metabolic syndrome, and type 2 diabetes has been the subject of various studies, with a particular focus on changes in the regulation of glucose and insulin sensitivity." (PMID 38474354, 2024). "Krill oil supplementation reduced levels of triacylglycerol, total cholesterol and LDL-cholesterol and improved endothelial dysfunction, HDL-cholesterol profile and insulin sensitivity in subjects with type 2 diabetes." (PMID 39555189, 2024). "Inhibiting lipase is a strategy to manage obesity and type 2 diabetes, as it reduces lipid levels and relieves stress on pancreatic β-cells, improving insulin regulation." (PMID 39598457, 2024). "The number of patients with type 2 diabetes, to whom insulin was administered, considerably increased during follow-up (70% vs. 21% at presentation)." (PMID 39063405, 2024). "Type II diabetes mellitus (T2D) is a chronic metabolic disorder characterized by hyperglycemia because of insulin resistance and insufficient compensatory insulin secretion." (PMID 38213906, 2024). "Pathways related to adipocytokine signalling, apoptosis, insulin signalling, and maturity onset diabetes of the young were examined." (PMID 39072272, 2024). "Excessive intake of fatty acids can result in a condition known as lipotoxicity (harmful effect of fats on cells), which can harm pancreatic beta cells (cells that produce insulin) and contribute to type 2 diabetes." (PMID 38297165, 2024). "A retrospective analysis of 728 people with type 2 diabetes on non-insulin therapies using isCGM found a 1.6 pp (16 mmol/mol) HbA1c reduction (p<0.001); a limitation of this analysis was the lack of a control group." (PMID 38951212, 2024). "This is a retrospective cohort analysis of approximately two million people with type 2 diabetes receiving insulin across 97 healthcare organisations using a global federated health research network (TriNetX, Cambridge, USA)." (PMID 38584180, 2024).
type 2 diabetes (continued). "Its role in insulin signaling pathways is particularly important in the development of type 2 diabetes, as it impacts the efficiency of insulin receptor signaling and glucose uptake, thereby modulating the body’s insulin sensitivity." (PMID 38610028, 2024). "The revolution in the therapeutic approach to type 2 diabetes (T2D) requires a rethinking of the positioning of basal insulin (BI) therapy." (PMID 38767675, 2024). "Type 2 diabetes is a chronic metabolic disorder characterized by high blood glucose levels due to either insufficient insulin production or ineffective utilization of insulin by the body." (PMID 38474306, 2024). "In this large, 10 week observational study, adults with type 1 diabetes and insulin-treated type 2 diabetes undertook meticulous thrice-daily reporting of their daily functioning using the Hypo-METRICS app and wore blinded CGM." (PMID 39080044, 2024). "Identifying novel miRNAs, particularly those involved in energy metabolism and insulin secretion, will shed light on the pathogenesis of type 2 diabetes." (PMID 38805166, 2024). "While basal glycogen synthesis was unaffected by roxadustat, pretreatment with roxadustat enhanced insulin-stimulated glycogen synthesis in myotubes from donors with type 2 diabetes (p=0.0345)." (PMID 38814443, 2024). "Magnesium, present in many foods but particularly in high-carbohydrate grains and pulses, is involved in insulin secretion and sensitivity mechanisms; a normal magnesium status protects against type 2 diabetes." (PMID 38967675, 2024). "By integrating imputation algorithms, the RF classifier was able to accurately predict type 2 diabetes subtypes even for individuals with missing insulin-related variables." (PMID 39168869, 2024). "These medications are commonly used in patients with type 2 diabetes either to help the body produce its own insulin or improve responsiveness to insulin, lowering blood sugar over time." (PMID 39479136, 2024). "In contrast, those with Type 2 diabetes have normal or even elevated insulin secretion from the β-cells compared to healthy individuals." (PMID 39950097, 2024). "The findings in our patient support these previous findings of dose-dependent improvement in glycemic control and insulin secretion capacity by sitagliptin observed in type 2 diabetes, and further show its effect on PNDM." (PMID 39430732, 2024). "The primary goals include maintaining good nutrition, a balanced weight, normal cholesterol levels, and effective insulin management, which are essential considerations in type 2 diabetes." (PMID 38357071, 2024). "Type 2 diabetes mellitus (T2DM) causes atherosclerosis in large and small blood vessels due to hyperglycemia and insulin resistance." (PMID 39364523, 2024). "Glycaemic control crucially depends on the timely identification of patients with type 1 diabetes and universal access to insulin for all patients, including those with poorly controlled type 2 diabetes." (PMID 39063405, 2024). "The results show a significantly faster increase in the proportion with insulin treatment over time among individuals with cancer and type 2 diabetes compared with type 2 diabetes controls." (PMID 39020360, 2024). "At the same time, MD was correlated with an improvement in insulin sensitivity and a decrease in blood glucose levels, an essential aspect in the prevention and treatment of type 2 diabetes in children and adolescents." (PMID 39723164, 2024). "Due to its central role in the secretion of insulin, the inwardly rectifying potassium channel subfamily J member 11 (KCNJ11) gene is one of the essential genes for predisposition to type 2 diabetes (T2D)." (PMID 39195547, 2024). "Although INS VNTR has been associated with type 2 diabetes (T2D), the results remain controversial." (PMID 37624484, 2024). "IR, characterized by hyperglycemia and high insulin levels, serves as the primary trigger in the onset of most type 2 diabetes cases." (PMID 38889391, 2024).
type 2 diabetes (continued). "Compared to sustainers, quitters tended to be older, women, nondrinkers, and light smokers, engage in more regular exercise, have more comorbid conditions and longer duration of type 2 diabetes, and use multiple oral antidiabetic agents and insulin." (PMID 38198206, 2024). "Type 2 diabetes mellitus is characterized by hyperglycemia, insulin resistance, and insufficient insulin production, marking it as a chronic metabolic disorder." (PMID 39634981, 2024). "The activation of BAT and browning of WAT accelerates glycolipid intake, reduces the requirement for insulin secretion, and improves glycolipid metabolism and insulin resistance in patients with obesity and type 2 diabetes." (PMID 39409659, 2024). "In the development of Type 2 diabetes, elevated insulin levels increase ROS levels, activate NLRP3 inflammasomes, and trigger subsequent inflammatory responses." (PMID 39619569, 2024). "Our findings contrast with those of a study using the glucose clamp technique to report an increase in insulin sensitivity after magnesium supplementation in people with type 2 diabetes." (PMID 37922013, 2024). "Higher insulin levels in type 2 diabetes (T2D) can result in lipolysis of adipose tissue activating lipid synthesizing enzymes such as fatty acid synthase and stearoyl-CoA desaturase-1, resulting in lipid accumulation in liver." (PMID 40630828, 2024). "This is analogous to the “Athlete’s Paradox,” where highly insulin-sensitive, endurance-trained athletes have skeletal muscle lipid levels similar to that observed in insulin-resistant obese and type 2 diabetes subjects." (PMID 38656127, 2024). "Fasting insulin levels and WHR were enriched in the adipose model SGBS_diff, indicating differing genetic impacts on metabolic physiology between type 2 diabetes and associated risk factors." (PMID 39240351, 2024). "Pioglitazone is an agonist of peroxisome proliferator-activated receptor gamma (PPARγ) and a known insulin sensitizer, primarily used to treat type 2 diabetes." (PMID 38078368, 2024). "In vitro experiments in pancreatic β-cells demonstrated that the overexpression of miR-19a-3p enhanced cell proliferation and insulin secretion and inhibited apoptosis, supporting miR-19a-3p as a candidate for managing type 2 diabetes." (PMID 38612989, 2024). "The studies revealed positive effects of FMT in type 2 diabetes, which is characterized by declining levels of blood glucose, HbA1c, and increased levels of Insulin and C peptide." (PMID 39483608, 2024). "Omental fat reduction should be considered as a clinical marker of insulin-sensitizing agents as Metformin or Dapaglifozin beneficial effect, in type 2 diabetes patients with obesity." (PMID 38734755, 2024). "Expression of Mfn2 was reduced in skeletal muscle of obese and lean type 2 diabetic patients compared to lean insulin sensitive individuals." (PMID 38478198, 2024). "In the SURPASS-3 study, individuals with inadequately managed type II diabetes mellitus were randomized to receive once-weekly tirzepatide or once-daily insulin degludec as an adjuvant to metformin." (PMID 39457606, 2024). "The study included MA enrollees with type 1 or type 2 diabetes and prescription claims for insulin between 2014 and 2018." (PMID 36992575, 2024). "Sufficient daily intake of magnesium can aid in restoring the optimal concentration of magnesium within cells, resulting in increased insulin-mediated glucose uptake in people with type 2 diabetes." (PMID 38525719, 2024). "In the context of type II diabetes mellitus, people who lose a similar amount of weight through calorie restriction experience an increase in insulin sensitivity, which mainly contributes to the enhancement of their glucose profile." (PMID 39457606, 2024). "Timely and effective use of basal insulin is essential for glycemic management and prevention of complications in patients with type 2 diabetes." (PMID 39629047, 2024).